SOD1 (superoxide dismutase 1)
Diseases named in the same sentence as SOD1 in open-access papers (continued):
Sharing a sentence is not in itself a finding about the gene and the disease.
prion disease (25 papers, 2010 to 2025). A transmissible disease that is caused by a protein that is able to induce abnormal folding of normal cellular proteins, leading to characteristic spongiform brain changes, which are associated with neuronal loss without an inflammatory response. "In this study we looked for an association between App, Il1-r1 and Sod1 representative SNPs and prion disease incubation time in the Northport heterogeneous stock of mice inoculated with the Chandler/RML prion strain." (PMID 23349894, 2013). "In this study we have shown a highly significant association with the Sod1 locus and prion disease incubation time thereby confirming its effect on the natural variation within these inbred lines of mice." (PMID 23349894, 2013). "For example, Sod1, encoding superoxide dismutase 1 (SOD1), which may release ROS stress, is frequently monitored in prion diseases." (PMID 37805966, 2023). "That is, in cell culture, seeding aggregation has been demonstrated for non-prion disease amyloids such as Tau, α-synuclein, amyloid-beta (Aβ), huntingtin, superoxide dismutase 1 (SOD1) or TDP-43." (PMID 35877764, 2022). "In that case, the resulted dimer eventually aggregates to the cytoplasmically segregated SOD1 proteins, similar to plaque formation in prion disease neurons." (PMID 31771229, 2019). "We have also confirmed the role of Sod1 as a protective factor in prion disease as deletion of Sod1 significantly reduces incubation time in two different strains of mouse adapted scrapie (Chandler/RML and ME7) and a mouse passaged BSE prion strain, MRC2." (PMID 23349894, 2013). "This includes PrPC for prion diseases, superoxide dismutase 1 for ALS, α-synuclein for PD, β-amyloid peptides for AD, and expanded polyQ Huntingtin in HD." (PMID 24228054, 2013). "It was previously reported that overexpression of human SOD1 in a transgenic mouse model increased prion disease incubation time with the RML prion strain, however, this was not replicated with the 301 V (BSE passaged in Prnpb allele mice, B6.I) strain." (PMID 23349894, 2013). "Additionally, prion diseases involve the misfolding of the PrPC protein, and ALS is associated with the misfolding of superoxide dismutase 1 (SOD1) and TDP-43." (PMID 39484301, 2024). "Interestingly, two genes, HSPA5 and SOD1, involved in prion disease, which is also a neurodegenerative disease with pathogenesis similar to AD, were also enriched." (PMID 33250918, 2020). "Our data confirm the protective role of endogenous Sod1 in prion disease." (PMID 23349894, 2013). "We have shown that variation at the Sod1 locus is associated with prion disease incubation time and that this is not explained by differences in mRNA expression levels." (PMID 23349894, 2013). "Slowing down or even halting disease progression after onset could be achieved by identifying compounds that inhibit amyloid formation either by stabilizing the native conformation of SOD1 or by directly inhibiting the fibrillization process, as proposed in prion disease." (PMID 20498711, 2010). "Sod1, superoxide dismutase 1 that is related to ALS is composed to HD and Prion diseases." (PMID 25561935, 2015). "We cannot exclude the possibility that the targeted knockout of Sod1 in these mice may inadvertently affect the expression of adjacent loci which themselves influence prion disease incubation time and that this would explain the absence of detectable differences in Sod1 expression." (PMID 23349894, 2013).
osteoporosis (24 papers, 2007 to 2026). A condition of reduced bone mass, with decreased cortical thickness and a decrease in the number and size of the trabeculae of cancellous bone (but normal chemical composition), resulting in increased fracture incidence. "Previous studies have shown that ROS accumulation caused by SOD1 dysregulation can lead to increased bone mass reduction, skeletal fragility, and low-turnover osteoporosis in long bones." (PMID 33613826, 2021). "Although both global knockout of cytoplasmic Sod1 as well as osteocyte-specific knockout of mitochondrial Sod2 seem to result in an osteoporosis-like phenotype in mice, several studies imply differences in the expression and the role of these antioxidative enzymes in bone." (PMID 35394023, 2022).
inflammatory bowel disease (23 papers, 2008 to 2025). A spectrum of small and large bowel inflammatory diseases of unknown etiology. "Overproduction of reactive oxygen species and antioxidant superoxide dismutases (SOD1, SOD2) dysregulation contribute to chronic inflammation such as generated in inflammatory bowel diseases (IBD)." (PMID 40000394, 2025).
leukemia (23 papers, 2002 to 2025). A malignant (clonal) hematologic disorder, involving hematopoietic stem cells and characterized by the presence of primitive or atypical myeloid or lymphoid cells in the bone marrow and the blood. "Broadly, these results show that loss of SOD1 confers a disadvantage to leukemia cells that is markedly amplified in the context of the PPM1D-truncating mutation." (PMID 38896450, 2024). "Altogether, our results demonstrate a role for SOD1 in the survival of PPM1D-mutant leukemia cells and highlight a new potential therapeutic strategy against PPM1D-mutant cancers." (PMID 38896450, 2024). "The median survival of mice transplanted with WT, WT/SOD1–/–, PPM1Dmut, and PPM1Dmut/SOD1–/– leukemia cells was 32, 43, 32, and 55 days, respectively; Mantel-Cox test, **p<0.01, ***p<0.001." (PMID 38896450, 2024). "Regarding AML, SOD1 overexpression has been associated with an adverse prognosis, and indirect inhibition of SOD1 resulted in selective apoptosis of leukemia cells." (PMID 37958462, 2023). "When combining our findings with existing research on leukemia cell lines, in becomes evident that SOD1 is an attractive candidate for further investigation as a therapeutic target for CK patients." (PMID 37958462, 2023). "SERPINA5 was significantly overexpressed in testicular cancer, Hodgkin’s disease, and lymphoma groups, while SOD1 was underexpressed in leukemia and lymphoma cancer compared to fertile men." (PMID 32942548, 2020). "Western blot analysis revealed an underexpression of SOD1 in Hodgkin’s disease, leukemia and lymphoma cancer groups." (PMID 32942548, 2020). "SOD1 is a synthetic-lethal vulnerability of PPM1D-mutant leukemia cells." (PMID 38896450, 2024). "Targeting SOD1 may have implications for inhibiting the growth and proliferation of leukemia cell lines with CKs as well as resistance to drugs such as venetoclax." (PMID 37958462, 2023). "(A,B) Dose response curves for cell viability with SOD1-inhibitor (LCS-1) (A) or LCS-1 in combination with 0.25 uM NAC (B) in WT and PPM1D-mutant leukemia cell lines after 24-hours." (PMID 38896450, 2024). "When SOD1 was deleted, the survival of mice transplanted with PPM1D-WT leukemia cells increased to a median of 43 days." (PMID 38896450, 2024). "Right: Kaplan-Meier survival curve of mice transplanted with WT or PPM1D-mutant (gray) leukemia cells with or without SOD1 deletion." (PMID 38896450, 2024). "Another SOD1 inhibitor is the estrogen derivative 2-methoxyoestradiol (2-ME), which induces ROS production and selectively kills human leukemia cells while sparing normal lymphocytes; however, 2-ME does not bind SOD1, as initially suggested, but interfered with the assay read-out." (PMID 32605023, 2020). "To test if SOD1 deletion affected the fitness of PPM1Dmut vs WT leukemia cells in vivo, we transplanted PPM1D-mutant and -WT OCI-AML2 cells with or without SOD1 deletion into immunodeficient (NSG) mice." (PMID 38896450, 2024).
Parkinson (22 papers, 2014 to 2025). "Indeed, the reports from human Parkinson’s brain and animal PD models suggest that Cu deficiency is associated with PD pathology, impaired SOD1 and COX activities, and increased cellular oxidative stress." (PMID 36077284, 2022).
anemia (21 papers, 2010 to 2025). A reduction in the number of red blood cells, the amount of hemoglobin, and/or the volume of packed red blood cells. "Unexpectedly, Sod1−/− mice administered allopurinol exhibited significant bone loss, anemia, fatty liver, and muscle and skin atrophy compared with WT mice." (PMID 33805516, 2021). "Neither XO-type- nor XDH-type KI mutants altered aging-like phenotypes, such as anemia, fatty liver, muscle atrophy, and bone loss, in Sod1−/− mice." (PMID 33805516, 2021). "A recent study reported that oxidative-stress triggers dysfunction of the proteasomal system and accelerates the accumulation of damaged proteins, leading to a shortened lifespan of RBCs and, hence, anemia in Sod1-deficient mice." (PMID 28000754, 2016). "What is more, measurement of related cofactors that may influence SOD-1 activity, such as anemia, vitamin deficiency, or trace elements of Cu and Zn, are needed." (PMID 39330521, 2024). "Furthermore, Sod1−/− mice exhibited various tissue pathologies, including anemia, fatty liver, muscle atrophy, bone loss, and skin atrophy." (PMID 33805516, 2021). "It was shown that SOD1 protects erythrocytes from the oxidative modification of proteins and lipids, resulting in anemia and the compensatory activation of erythropoiesis." (PMID 33019780, 2020). "SOD1 is an isoenzyme involved in the defense of red blood cells against protein and lipid oxidation, in which structural changes may contribute to anemia or activation of erythropoiesis." (PMID 35205334, 2022). "Finally, the oral administration of KP to Sod1-deficinet mice, which is a good mouse model of age-related disease, clearly ameliorated various pathologies, including skin thinning, fatty liver and anemia." (PMID 29915223, 2018). "Over expression of miR-144 is associated with severity of anemia and decreased hemoglobin/hematocrit cell count, and also leads to the lack of antioxidant proteins such as glutamate-cysteine ligase, catalytic/modifier subunit (GCLC/M) and superoxide dismutase 1 (SOD1)." (PMID 26862517, 2016).
glaucoma (21 papers, 2011 to 2025). Increased pressure in the eyeball due to obstruction of the outflow of aqueous humor. "In this fluid, decreased expression of SOD1/2 as well as of GST were observed in glaucoma patients in comparison to cataract control group." (PMID 30524222, 2018). "Among the identified proteins significantly altered in glaucoma, eight were further studied using semi-targeted or targeted approaches, showing higher levels of ALB, APOC3, CysC, TIMP2, A2M, PGTDS, and ENPP2, and lower levels of SOD1, in POAG patients compared to control subjects." (PMID 34439995, 2021). "Furthermore, some previous identified glaucoma autoantigens including heat shock protein 60 dDA (HSPD1), heat shock protein 70 kDa (HSPA1B), vimentin (VIM), α-enolase (ENO1) and superoxide dismutase 1 (SOD1) could be detected." (PMID 30899261, 2019).
multiple sclerosis (21 papers, 2012 to 2025). A progressive autoimmune disorder affecting the central nervous system resulting in demyelination. "SOD1 deficiency is associated with oxidative distress in Multiple Sclerosis, an autoimmune demyelinating disease, evidencing the importance of this molecule in maintaining normal function of the central nerve system." (PMID 37760050, 2023). "Transcripts of superoxide dismutase 1 (SOD1), mutations in which are implicated in multiple sclerosis, a de-myelinating disease, were upregulated 1.7-fold (P<0.001) in Schwann cells." (PMID 26251357, 2015). "Furthermore, memantine has shown promise in modulating oxidative stress by stimulating the SOD1-relevant anti-oxidant defense system in experimental autoimmune encephalomyelitis (EAE), a model for multiple sclerosis." (PMID 39850115, 2025).
neuropathy (21 papers, 2012 to 2026). A disorder affecting the nervous system that manifests with pain, tingling, numbness, and/or muscle weakness. "Notably, two patients exhibited digenic inheritance involving MFN2 and either PMP22 or SOD1, highlighting the genetic complexity underlying inherited neuropathies." (PMID 41030121, 2026). "It is also possible that the neuropathy develops because of a loss-of-unknown SOD1 function." (PMID 25468678, 2015). "The first mention of SOD1-related neuropathy appeared in 2003, when two familial ALS cases were found to have concurrent sensory neuropathy." (PMID 39932579, 2025). "In accordance with our findings, the administration of CoPP also normalized the down-regulation of Nrf2, HO-1, and SOD-1 detected in the AMG of diabetic animals with neuropathy." (PMID 37891937, 2023). "This association is supported by pre-clinical studies; in particular, it is known that mice models of SOD1 ALS have demonstrated the presence of neuropathy." (PMID 37610446, 2023). "SOD1 is a superoxide radical scavenger that may confer some protection against HIV-1 neuropathy as part of the oxidative stress response, but which has no described associations with HIV-1 restriction factors." (PMID 28061811, 2017). "Interestingly, the selective targeting of wild type SOD1 in IMS of the knockout SOD1 mouse prevented the development of motor neuropathy and preserved axonal maintenance." (PMID 26379505, 2015). "Our results indicated that inhibition of SOD1 prevents BM-MSCs from rescuing neuropathy in a paracrine manner, which suggests that SOD1 could be a major part of their neuroprotective mechanism of action along with their ability to reduce inflammation and plexitis." (PMID 38503815, 2024). "Alternatively, the NRF2 transcription factor serves as a pivotal regulator of the endogenous antioxidant defense and the activation of its downstream target genes, such as HO-1, SOD-1, and GSTM1, is crucial for regulating neuropathy induced by chemotherapy." (PMID 39061924, 2024). "The other two patients with possible SOD1-negative familial ALS had a rather aggressive disease course, with coexisting CIDP-like neuropathy beginning before ALS, no response to IVIG therapy, and death at 13 and 20 months from onset respectively." (PMID 37610446, 2023).
cardiomyopathy (20 papers, 2010 to 2026). A disease of the heart muscle or myocardium proper. "However, in marked contrast to worms, SOD2 or SOD1 knockout in mice develop cardiomyopathy, neurodegeneration, or neuromuscular junction degeneration, respectively, and decreased lifespan, while neither SOD1 nor SOD2 overexpression in mice extends lifespan." (PMID 27114848, 2016). "In mammals, SOD1-deficient mice appear normal at birth but show increasing levels of oxidative stress over time, while SOD2-knockout mice can only live for a short span (10 days) before showing cardiomyopathy, as SOD2 responds to numerous inflammatory and oxidative stimuli." (PMID 25714339, 2015). "In addition, the myocardial antioxidation proteins (Nrf2, HO‐1, SOD1, SOD2), Sirt1 (a regulator of cellular ageing, apoptosis, stress, etc) and pAMPK (a regulator of cellular energy homeostasis) were down‐regulated in mouse hearts with doxorubicin cardiomyopathy." (PMID 32918384, 2020).
fibrosis (20 papers, 2014 to 2025). the formation of excess fibrous connective tissue in an organ or tissue in a reparative or reactive process. "The gene expressions of superoxide dismutase (SOD1; SOD2) and glutathione peroxidase (GPx1) were evaluated using real-time PCR in advanced fibrosis (AF: F3F4) in patients with PBC." (PMID 38671835, 2024).
malaria (20 papers, 2010 to 2025). Malaria is a serious and sometimes fatal disease caused by a parasite that commonly infects a certain type of mosquito which feeds on humans. "TNF-α was associated with IFN-γ, sTNF-RI, SOD-1 and HO-1, implying a potential interplay between those mediators in the pathogenesis of malaria-related symptoms." (PMID 23433077, 2013). "The preliminary data from our group showed an association between several SNPs in the SOD-1 gene and different expressions of this enzyme in subjects with malaria." (PMID 23316245, 2012). "Nevertheless, during experimental malaria, mice overexpressing SOD-1 develop oxidative injury associated with increased vulnerability to P. berghei." (PMID 20386593, 2010). "Furthermore, those SOD-1 SNPs were associated with malaria symptoms in individuals infected with P. vivax, indicating that the genetic predisposition of the individual might alter the response of these subjects against ROS." (PMID 23316245, 2012). "Other molecules circulating in plasma, such as adhesion molecules, pro-inflammatory cytokines, the superoxide dismutase-1, and, more recently, microparticles, have been suggested as biomarkers for human P. vivax malaria as their levels are often associated with malaria clinical manifestations." (PMID 21611202, 2011). "Interestingly, we found an elevation in SOD-1 abundance and activity in the severe malaria patients." (PMID 27090372, 2016). "Thus, SOD-1 connectivity seen herein in severe malaria patients seems to be a response against the high production of deleterious haem during the robust intravascular haemolysis observed in severe malaria." (PMID 23433077, 2013). "Indeed, it has been described that both glutathione and catalase might be reduced during severe malaria and high levels of SOD-1 could lead to the exacerbation of the oxidative stress and inflammation, aggravating the outcome of the disease." (PMID 23433077, 2013). "SOD-1 levels were much more effective in predicting vivax malaria severity than TNF-alpha, a major cytokine related to malaria clinical severity in P. vivax infections." (PMID 20386593, 2010). "To date, no strong evidence of the clinical utility of biomarkers is available for Pv-SM even though some of them such as superoxide dismutase 1 (SOD), titin, vitronectin, TNF-α, and the Ang-2/1 ratio have shown interesting performances for the prognosis of malaria severity." (PMID 36036460, 2022). "In addition, the release of haem during malaria erythrocytic cycle reduces the production of anti-inflammatory prostaglandin E2 and TGF-β from mononuclear cells via SOD-1." (PMID 23433077, 2013). "In the group of individuals presenting with severe non-lethal malaria, parasitaemia displayed significant positive associations with TNF, sTNF-RI, IFN-γ, IL-10, CXCL9, CXCL10, SOD-1 and HO-1, while negatively correlated with the chemokines IL-8 and CCL2." (PMID 23433077, 2013). "SOD-1 is a powerful predictor of malaria severity in individuals infected with P. vivax with higher sensitivity and sensibility than TNF-α levels, confirming the importance of this enzyme in malaria pathogenesis." (PMID 23316245, 2012). "This study illustrates the possibility of using SOD-1 levels as a severity biomarker in human P. vivax malaria and highlights the likelihood of exploring the future use of the plasma SOD-1 levels as an effective marker of malaria severity." (PMID 20386593, 2010).